NRG1 (neuregulin 1)
Diseases named in the same sentence as NRG1 in open-access papers (continued):
Sharing a sentence is not in itself a finding about the gene and the disease.
schizophrenia (continued). "Accumulating evidence from human genetic studies has suggested several functional candidate genes that might contribute to susceptibility to schizophrenia, including AKT1 and neuregulin 1 (NRG1)." (PMID 25688191, 2014). "Interestingly, postmortem studies have reported alterations in BDNF, NRG1 and their receptors in prefrontal cortex of schizophrenia subjects indicating their roles in the pathophysiology of this disorder." (PMID 25052836, 2014). "Interestingly, schizophrenia patients show altered expression of both the ErbB family of receptors for NRG1 and NMDARs." (PMID 25324742, 2014). "Since the dendritic length of interneurons is reduced in schizophrenia, understanding how NRG1/ErbB4 signaling regulates the dendrites of these cells may help clarifying the mechanisms underlying the cortical defects in this disorder." (PMID 25309333, 2014). "In Experiment 2, based upon major neurotransmitter-based hypothesis of schizophrenia, 3 related drugs were chosen to evaluate drug-induced behavioral alterations in our novel TMc-Nrg1+/−mutant mice." (PMID 24782733, 2014). "A study investigating a population of carriers of the NRG1 (valine to leucine) mutation has observed increased circulating proinflammatory cytokines, including IL-6, TNF-α, and IL-1b suggesting a role of this mutation in immune dysregulation in schizophrenia." (PMID 23805069, 2013). "Furthermore, abnormal proteins encoded by schizophrenia susceptibility genes (PRODH, DISC1, DAOA, NRG1, G72) cause oxidative stress and/or hypersensitivity to oxidative stress or mitochondrial dysfunction." (PMID 24027504, 2013). "In NRG1, a significant 25-kb block, between 32,291,552 and 32,317,192, was associated with risk of schizophrenia in all CATIE, GAIN, and nonGAIN datasets (p = 0.0005, 0.0589, and 0.0143, respectively)." (PMID 23301017, 2013). "Interestingly, another microarray gene expression investigation using whole blood from patients with schizophrenia and assessing gene expression changes related to positive symptomatology, found that NRG1 was increased relative to higher delusional states." (PMID 23805071, 2013). "We did find significant association of NRG1 and DAO genes with schizophrenia." (PMID 23555897, 2013). "The possibility that genes confer vulnerability to Δ9-THC effects on cognitive processing also finds support in animal research where heterozygous Neuregulin 1 knockout mice have been observed to show differential sensitivity to the acute effects of Δ9-THC on behavioral phenotypes of schizophrenia." (PMID 24391602, 2013). "Neuregulin-1 (NRG1) is another candidate gene for schizophrenia." (PMID 23805069, 2013). "Additionally, AKT protein levels and phosphorylation of GSK3β are altered and NRG1-stimulated phosphorylation of AKT is reduced in schizophrenia." (PMID 23543703, 2013). "Researchers have identified a number of genetic variants that predispose the brain to developing schizophrenia, with vulnerability in DISC1 and NRG1 the best replicated in association with a developmental hypothesis." (PMID 23805069, 2013). "Besides, we have also performed the association studies in Taiwanese samples on NRG1 (8p12), DAO (12q24), and DAOA (12q33.2) as these three genes were reported to have strong association with schizophrenia in the literature." (PMID 23555897, 2013). "There is additional evidence in the literature of region specific changes in NRG1 in schizophrenia." (PMID 22590542, 2012). "We hypothesised that CBD treatment would attenuate the hyperlocomotor activity of Nrg1 mutant mice, which is relevant to the psychomotor agitation observed in the ‘positive’ signs of schizophrenia." (PMID 22509273, 2012). "In particular, susceptibility genes underlying the pathogenesis of schizophrenia, such as Disrupted-in-schizophrenia 1 (DISC1) and Neuregulin 1 (NRG1), are increasingly being examined within zebrafish to provide novel insights into their role in brain development." (PMID 23449968, 2012).
schizophrenia (continued). "In this way, we provide a means by which Type III Nrg1 signaling in the periphery could contribute to deficits in pain sensing seen in schizophrenia patients." (PMID 21949864, 2011). "NRG1 is located on 8p, a region whose linkagewith schizophrenia has been consistentlyreported." (PMID 23508206, 2011). "In addition to shedding insight into the function of Type III Nrg1 in sensory neurons, these findings provide a potential biological mechanism for some of the abnormalities in pain sensation seen in patients with schizophrenia." (PMID 21949864, 2011). "It is noteworthy that there has been no report on the NRG1 associationwith schizophrenia in a population from the Middle East region." (PMID 23508206, 2011). "Strong association between NRG1 and schizophrenia was also found in Chinese population, but not in Japanese population." (PMID 22937274, 2011). "This is a single marker association studybut it would be interesting to include more SNPsand perform haplotype analysis of the 5' end ofthe NRG1 gene in order to bring new evidenceabout the possible role of haplotypes of Hapicein the pathology of schizophrenia." (PMID 23508206, 2011). "NRG1-mediated erbB signaling has important roles in neural and glial development, as well as in the regulation of neurotransmitter receptors thought to be involved in the pathophysiology of schizophrenia." (PMID 22937274, 2011). "Conversely, the present NRG1-Tg mice, which display the increases in these pathological markers, may be irrelevant to an animal model for schizophrenia in spite of their schizophrenia-like behavioral deficits." (PMID 21151609, 2010). "Thus, these patient studies rather suggest a biological link between increased NRG1 signaling and the pathophysiology of schizophrenia." (PMID 21151609, 2010). "Moreover, EGR3 is a downstream gene of many signaling pathways including pathways triggered by NGF, BDNF and NRG1, of which BDNF and NRG1 are schizophrenia susceptibility genes." (PMID 20156358, 2010). "Moreover, it was shown that genetic variation in the catechol-O-methyltransferase (COMT) and the neuregulin-1 (NRG-1) proteins influences PPI in schizophrenia patients and healthy volunteers." (PMID 19545856, 2009). "In addition to providing further evidence of NRG1 and ERBB4 associations to schizophrenia, our study is the first to suggest possible involvement of three additional genes from the NRG and ERBB gene families, i.e. NRG2, NRG3 and EGFR (ERBB1)." (PMID 17598910, 2007). "The strong relationship between the NRG1-induced adhesion response and the ability of the cells to migrate has potential implications for several clinical disease entities, most notably cancer and schizophrenia." (PMID 18159252, 2007). "Furthermore, several recent reports suggest association between schizophrenia and single-nucleotide polymorphisms (SNPs) in ERBB4, one of the receptors for Neuregulin-1." (PMID 17598910, 2007). "Although it is not currently known whether any schizophrenia-associated genes are specifically linked to the myelination of GABAergic interneurons, NRG1–ErbB4 signaling represents a compelling candidate." (PMID 40410588, 2025). "Schizophrenia subjects exhibited thousands of neuronal and non-neuronal epigenetic differences at regions that included several susceptibility genetic loci, such as NRG1, DISC1, and DRD3." (PMID 38648100, 2024). "In addition, one research study has revealed that the haplotype Nrg1 causes a strong expression of Nrg1 type III in the brain, which may cause the pathogenesis of schizophrenia." (PMID 38136627, 2023). "A previous study found that NRG1 mRNA expression in peripheral lymphocytes is abnormally low in first onset schizophrenia, and that this expression gradually increases in antipsychotic treated patients, demonstrating that NRG1 mRNA may serve as a potential therapeutic marker." (PMID 35337293, 2022).
schizophrenia (continued). "However, whether NRG1 upregulation contributes to GABAergic maturation defects in FGR induced schizophrenia is still unclear." (PMID 36460658, 2022). "In various studies, only a few of them, such as DISC1 (Disrupted-In-Schizophrenia 1), COMT (Catechol-O-Methyltransferase), VMAT1 (Vesicular Monoamine Transporter 1) or NRG1 (Neuregulin 1), could be sufficiently confirmed as relevant for schizophrenia development." (PMID 35053755, 2021). "Similarly, NRG1 is associated with promoting metastasis of HCC cells by increasing epithelial-mesenchymal transition, thus increasing migratory behavior of the cancer cells (genetic variants in NRG1 have also been associated with schizophrenia)." (PMID 33557409, 2021). "Furthermore, both elevated and reduced NRG1 levels were reported in patients with schizophrenia." (PMID 33708250, 2021). "Thus, we speculated that NRG-1 was a potential target for the therapeutic effect of SZASD on schizophrenia." (PMID 33708250, 2021). "Enhanced NRG1 signaling may contribute to NMDAR hypofunction in schizophrenia." (PMID 33552387, 2021). "In addition, NRG1 gene is a candidate gene for schizophrenia." (PMID 32690068, 2020). "Specially, in the Asian population, several studies have suggested that NRG1 rs6994992 may not be a schizophrenia risk variant." (PMID 31649580, 2019). "The advantage of this anti-Nrg1 antibody model over the more widely used genetic, pharmacological or lesion models is that schizophrenia-like phenotypes can be induced in the adult mice and thus offers one rare opportunity to study late/adult-onset schizophrenia model." (PMID 31653237, 2019). "However, since NRG1 rs6994992 is not a schizophrenia risk variant in the Han Chinese population, the validated association suggested that ethnic difference may exist in the relationship between NRG1 rs6994992, schizophrenia and creativity." (PMID 31649580, 2019). "It is possible that changes in 2-AG enzyme function may play a role in the development of schizophrenia-related phenotypes; however, this does not appear to depend on mutation in the NRG1 TM gene." (PMID 29467679, 2018). "Moreover, an unbalance of mGluR1-dependent LTD, due to altered NRG1/ErbB signaling in SNpc DA neurons, could contribute to the dysfunctions in the nigrostriatal DA transmission occurring in PD and schizophrenia." (PMID 30327588, 2018). "Importantly, Nrg1 TM HET mice also exhibit altered susceptibility to the behavioural and neural effects of cannabinoids, which is relevant to the increased cannabis sensitivity observed in patients with schizophrenia." (PMID 29467679, 2018). "However, this same study suggested that there may be an exaggerated NRG1 stimulated cytokine response from PBMC in people with schizophrenia compared to controls, suggesting a link between overactive NRG1 signaling and inflammation." (PMID 29163244, 2017). "NRG1 may have an anti-inflammatory and neuroprotective function via the up-regulation of α7 nicotinic acetylcholine receptor, a key component not only in neurotransmission and schizophrenia, but also in cholinergic anti-inflammatory responses." (PMID 28646138, 2017). "We expected that there would be multiple molecular changes in TRS compared to controls that may contribute to the amplification of NRG1 signaling in perhiperal blood in support of a widespread gain of function model of NRG1 in the pathophysiology of schizophrenia." (PMID 29163244, 2017). "In addition, a novel haplotype of the NRG1 gene was found to confer risk of schizophrenia susceptibility in Chinese Han, but not in the Icelandic/Scottish population." (PMID 28993723, 2017). "Axonal signaling by Nrg1 adds an additional layer of complexity to the role of these molecules in neuronal development and might provide additional insight into their contribution to the etiology of schizophrenia." (PMID 28275713, 2017).
schizophrenia (continued). "Taken together, these data suggest that NRG1 may play a modulatory role in both in the CNS and systemically and disruption of its signaling either intrinsic to the disease processes in schizophrenia and/or with APDs may lead to the neuropsychiatric and metabolic dysfunction observed clinically." (PMID 28804444, 2017). "Therefore, the targeted deletion of NRG1 provides novel insights into the role of NRG1 and supports that it may contribute to schizophrenia." (PMID 27047540, 2016). "Additionally, a missense mutation in NRG1 has been reported to increase activation of proinflammatory cytokines such as interleukin 6 (IL-6), tumor necrosis factor α (TNF-α), and interleukin 8 (IL-8) in patients with schizophrenia." (PMID 27725886, 2016). "Therefore, the mouse models based on NRG1 presented in this section help to identify the behavioral and mechanistic processes that may be relevant to the pathophysiology of schizophrenia." (PMID 27047540, 2016). "Previously, many candidate genes, including NRG1 (encoding neuregulin 1), AUTS2 (autism susceptibility candidate 2), TSPAN8 (Tetraspanin-8), ZNF804A (zinc-finger protein 804A), among others, have been identified that might confer risk for schizophrenia." (PMID 26016498, 2015). "Therefore, some interaction between the NRG1-ErbB4 signaling and other schizophrenia-related genes such as Reelin might occur during development." (PMID 26733804, 2015). "Consistent with the results of human studies, mice with selective ErbB3 receptor deletion in oligodendrocytes demonstrate deficits in social interaction and working memory, suggesting that NRG1-ErbB3 signaling in oligodendrocyte might contribute to the pathogenesis of schizophrenia." (PMID 26029044, 2015). "Neuregulin 1-ErbB receptor signaling appears to play a critical role in the ontogeny of psychiatric disorders and this hypothesis has been supported by the identification of altered expression levels and/or function of NRG1, ErbB3, and ErbB4 in patients with schizophrenia." (PMID 26029044, 2015). "Here, there was a tendency toward reduced [3H] MK-801 binding in the medial prefrontal cortex of Nrg1 HET mice which accords with the general view of NMDAR hypofunction in schizophrenia as well as research showing that NMDAR expression is reduced in the schizophrenia brain." (PMID 25324742, 2014). "NRG-1 is also associated with a non-deficit subtype of schizophrenia." (PMID 25566074, 2014). "We could not detect any significant influence of variation in NRG1/NRG3 polymorphisms on the cognitive performance of patients with schizophrenia." (PMID 24976857, 2014). "Furthermore, the present finding that the heart rate of patients with schizophrenia was increased compared to controls is consistent with previous reports and with the finding that the heart rate of mice with impaired NRG1 function was higher than that of control animals." (PMID 24887423, 2014). "Numerous roles for NRG1 in central nervous system development and function have been identified, but the precise functions of NRG1 signaling in the pathogenesis of schizophrenia remains unclear." (PMID 25688191, 2014). "Therefore, NRG1 could be a candidate factor for explaining the prolongation of the QT interval observed in the patients with schizophrenia in the present study." (PMID 24887423, 2014). "Contrary to our hypothesis, we could not detect any significant influence of variation in Neuregulin 1/Neuregulin 3 polymorphisms on cognitive performance or electrophysiological parameters of patients with schizophrenia." (PMID 24976857, 2014). "Therefore, NRG1 could contribute to cognitive dysfunction in schizophrenia by altering NMDAR function and/or affecting synaptic plasticity." (PMID 23543703, 2013). "Similarly, with respect to NRG1 haplotype block, binding of the TATA, instead of CDXA-E2F-HFH2, had a protective effect, whereas S8-CDXA-NKX2 binding to 3′ end of the block increased risk of schizophrenia in the European population." (PMID 23301017, 2013).
schizophrenia (continued). "We have investigated the effects of cannabis constituents in the transmembrane domain neuregulin 1 heterozygous mutant (Nrg1 TM HET) mouse, a model for a schizophrenia susceptibility gene that offers partial construct, predictive and face validity for schizophrenia." (PMID 22509273, 2012). "The association of schizophrenia and single-nucleotide polymorphisms (SNPs) of ERBB4 (v-erb-b2 erythroblastic leukemia viral oncogene homolog 4), enconding one of the receptors for NRG1 has been shown, thus suggesting that NRG1-ERBB signaling is involved in the pathogenesis of schizophrenia." (PMID 21637446, 2009). "Therefore, we investigated the impact of four SNPs, which were previously linked to sensorimotor gating and schizophrenia, on PPI in a new and independent sample of healthy human volunteers: The linked 5-HT2AR T102C/A-1438 G, the COMT Val158Met, and the NRG-1 Arg38Gln polymorphisms." (PMID 19545856, 2009). "However, it has been recently demonstrated that BACE1 knockout mice exhibit a number of schizophrenia-like behavioural traits, most likely because BACE1 is involved in the cleavage of neuregulin-1, which has been linked to the pathogenesis of schizophrenia and related psychiatric disorders." (PMID 18564425, 2008). "These new findings suggest that observed associations between NRG1 and schizophrenia may be mediated through functional interaction not just with ERBB4, but with other members of the NRG and ERBB families." (PMID 17598910, 2007). "Moreover, genome-wide association studies have reported various schizophrenia risk loci that have been used to create animal models, such as Disrupted-in-Schizophrenia 1 (DISC1), dysbindin-1, neurotrophic factor neuregulin 1 (NRG1) and its receptor, epidermal growth factor receptor 4 (ErbB4)." (PMID 39336117, 2024). "The neuregulin 1 transmembrane domain heterozygous (Nrg1 TM HET) mutant mouse shows face, predictive, and construct validity for schizophrenia." (PMID 36406747, 2022). "Moreover, alterations to the NRG1 and ErbB4 signaling pathways are involved in neuronal migration, regulation of synaptic plasticity and neural survival, which may be the neurobiological underpinnings of schizophrenia." (PMID 35337293, 2022). "This study highlights the role of the NRG1/ERbB4 and PI3K/AKT/mTOR signaling pathways in the neuroprotective effects of aripiprazole and sertindole on ketamine-induced schizophrenia in rats." (PMID 35876932, 2022). "This study investigates the effects of aripiprazole and sertindole on the NRG1/ErbB4 and PI3K/AKT/mTOR signaling pathways in ketamine-induced schizophrenia in rats." (PMID 35876932, 2022). "Extending these behavioral effects, THC induced different consequences in the binding density of CB1 and 5-HT2A receptors between Nrg1 HET and WT groups in brain areas related to schizophrenia." (PMID 34360626, 2021). "In this study, we first analyzed Nrg1 gene expression in the postmortem PFC and found increased type I Nrg1 expression in GABAergic interneurons from schizophrenia patients, compared with age- and sex-matched controls." (PMID 33436636, 2021). "Importantly, numerous independent studies have identified a genetic association of natural variants of NRG1, NRG3, and ErbB4 with schizophrenia, as well as with altered electrophysiological properties of inducible pluripotential stem cells isolated from schizophrenia patients." (PMID 32354758, 2020). "One study in 2012, provides evidence for link between the NRG1-ErbB4 signaling pathway and PIK3CD in schizophrenia." (PMID 31959813, 2020). "The mice that were hypomorphic for NRG1 also had fewer functional NMDA receptors in the brain, a feature observed in schizophrenia patients." (PMID 32425837, 2020). "Increasing evidence indicates that neuregulin 1 (NRG1) plays an important role in psychiatric illnesses, including depression, schizophrenia and bipolar disorder." (PMID 32703967, 2020).